EGFR (epidermal growth factor receptor)
Diseases named in the same sentence as EGFR in open-access papers (continued):
Sharing a sentence is not in itself a finding about the gene and the disease.
tumor (continued). "Now, we prove that the bile acid-EGFR-inflammation interacting axis could operate as well in cholestatic injury, a non-tumour context, having HPC as cellular mediator." (PMID 38725853, 2024). "Furthermore, under flow conditions, the exosomes decorated with nanobodies significantly enhanced the adhesion of cells to tumor cells that express EGFR." (PMID 38699435, 2024). "EGFR activation triggers signalling cascades, including the PI3K/Akt pathway, and its overexpression is common in many cancers including NPC, and is linked with tumour recurrence, migration, and poor prognosis in NPC." (PMID 39593139, 2024). "This method was used to characterize the percent of HER2-positive and EGFR-positive cells ex vivo in s.c. tumor xenografts in NOD-SCID mice formed by the inoculation of 100% SK-OV-3 or MDA-MB-468 cells or a mixture of 30% SK-OV-3 cells and 70% MDA-MB-468 cells." (PMID 38711454, 2024). "Although the precise molecular and cellular mechanisms underlying EGFR upregulation in CRC remain incompletely understood, omics data from CRC patient cohorts consistently show elevated EGFR expression levels in tumor tissues, which correlate with poor prognosis." (PMID 39695128, 2024). "In the last decade, preclinical and clinical cohort studies have uncovered genomic alterations that confer a selective advantage to tumor cells under EGFR blockade, mainly downstream re-activation of RAS-MEK signaling and mutations in the extracellular domain of EGFR (EGFR-ECD)." (PMID 38711991, 2024). "Furthermore, MAB100 also blocks EGFR’s downstream signaling as seen by a higher rate of apoptosis in AVID100-treated tumor cells compared to MAB100-treated tumor cells." (PMID 39456611, 2024). "Development of drug resistance to ALK-TKI leads to hyperactivation and development of secondary mutations in kinases such as EGFR, ERBB3, it is therefore worth exploring further the combination of ALK-TKI and ERRB inhibitors to overcome any emerge resistance of these tumours." (PMID 39695132, 2024). "Relatively low expression of GCLC in EGFR-overexpressing GBM may keep ROS at a threshold favorable for ROS tumor-promoting functions." (PMID 39001381, 2024). "In both KRAS wild-type and mutant subgroups, additional factors that could impact EGFR mAb efficacy were explored including the type of chemotherapy, line of therapy, age, sex, tumour sidedness and site of metastasis." (PMID 38402342, 2024). "By simultaneously disrupting mitotic control and EGFR signaling, this approach may effectively halt tumor progression, reduce resistance to treatment, and improve overall survival rates." (PMID 39339232, 2024). "Moreover, the combination of atorvastatin with EGFR-TKIs in the treatment of NSCLC demonstrated an enhanced anti-tumor effect in vitro, along with a mitigated growth of NSCLC in vivo." (PMID 39308527, 2024). "Similarly, the transfer of the mutated KRAS gene, along with other oncogenes such as EGFR, from colon cancer cells to recipient cells with wild-type KRAS occurs through exosomes, promoting tumor invasion." (PMID 38672455, 2024). "However, it is noteworthy that SchA exhibited higher binding affinity to wild‐type EGFR compared to mutant EGFR, suggesting potential side effects as an anti‐tumor drug." (PMID 38376003, 2024). "Eligible patients were adults diagnosed with HER2‐mutant mNSCLC from January 2014 to July 2021 without co‐occuring epidermal growth factor receptor (EGFR) tumor mutations." (PMID 39692700, 2024). "In summary, our multifaceted approach, incorporating new technologies such as scRNA-seq and ST as well as conventional cell line systems and animal models, highlights the importance of BCL2L1 expression in tumor cell survival as drug resistance emerges and cells acquire resistance to EGFR-TKI." (PMID 39122703, 2024). "Previous studies have reported that a right colon PTL is associated with a lack of benefit when treated with EGFR-inhibitors; additionally, when the tumor is RAS wt or RAS & BRAF wt and pMMR." (PMID 38473410, 2024).
tumor (continued). "However, the regulatory mechanism of TGF-β expression in EGFR-mutated NSCLC cells and its functional role in anti-tumor immunity and immunotherapy remain undetermined." (PMID 39004699, 2024). "Recently, the multifaceted function of tumor cell-derived exosomes has emerged as an important field in cancer research, and in this regard novel, non-canonical mechanisms of action have been reported for both the EGFR and ErbB2." (PMID 36817764, 2023). "EGFR dimerization may result in cancer cell proliferation, the inhibition of apoptosis, invasion, metastasis, and tumor-induced neovascularization." (PMID 37569812, 2023). "The anti-EGFR iEDNs-QD showed the most effective tumor imaging for 48 h after injection." (PMID 36839675, 2023). "In 24 serum exosome samples, circKIF20B was negatively correlated with tumor size (p = 0.018), negatively correlated with advanced tumor (p = 0.04), and circKIF20B was not significantly correlated with age, gender, and EGFR mutation." (PMID 37394466, 2023). "Dysfunctional EGFR signaling promotes the acquisition of cancer stem-like properties, including self-renewal, tumor heterogeneity, metastasis, resistance to chemotherapy and radiotherapy, and recurrence, by increasing the expression of CSC-related markers in NSCLC." (PMID 37298389, 2023). "High EGFR protein in PTC (high risk tumor) is not due to gene overexpression, but rather caused by accumulation of non-degraded protein arrested in endosomal compartments and disseminated through exosomes to the extracellular milieu." (PMID 37114127, 2023). "EGFR-amplified tumours have been shown to be more aggressive and may carry a vulnerability towards targeted EGFR therapies." (PMID 36765632, 2023). "Finally, all radiotracer candidates were evaluated in terms of tumor cell internalization and receptor binding potential on EGFR-positive A431 cell." (PMID 37259420, 2023). "In perspective, these peptides could be used to decorate drug delivery systems, such as peptide-drug conjugated nanoparticles, in order to target EGFR-positive tumor cells." (PMID 37048151, 2023). "Co-treatment of IL-6 with anti-PD-1 could enhance the activation of tumor-infiltrating Treg and Th17 in EMT-associated TKI-resistant EGFR-mutant NSCLC." (PMID 37345086, 2023). "Downregulation of SOCS3 may attenuate the inhibition of signaling pathways such as JAK/STAT and EGFR, promoting tumor cell growth and drug resistance." (PMID 37894282, 2023). "17864-NANAPs showed a 40-fold higher binding to EGFR-positive squamous head and neck cancer cells leading to the successful release in the tumour cell and inhibition of proliferation; in contrast, the non-targeted formulations had no antiproliferative effects on HNSCC cells." (PMID 36980527, 2023). "In these validation cases, DMEA not only identified the expected drug MOAs (e.g., EGFR inhibitor MOA given a signature of EGFR inhibitor resistance) but also MOAs which may exhibit toxicity against tumor cells resistant to the input signature of interest." (PMID 37226094, 2023). "Importantly, flunarizinewas also shown to significantly potentiate the tumor growth suppressiveeffect of gefitinib in EGFR TKI-refractory PDX in vivo." (PMID 37854628, 2023). "Additionally, the results indicated that PD-L1 expression was also associated with sex, smoking status, histology, differentiation, tumor size, lymph node metastasis, TNM stage, and EGFR mutation." (PMID 37305382, 2023). "The better anticancer effect of NPs-siLCN2 was further demonstrated by histological analysis, in which the NPs were the most effective in inhibiting tumor proliferation, silencing LCN2 expression, and suppressing p-EGFR and Ki67 expression in the tumor tissues." (PMID 36899380, 2023).
tumor (continued). "For example, tumor cells employ immune evasion by up-regulating PD-L1 expression, and the epidermal growth factor receptor (EGFR)-p38 mitogen-activated protein kinase (MAPK) pathway enhances PD-L1 levels via miR-675-5p and concurrently represses human leukocyte antigen-ABC (HLA-ABC) through HK II." (PMID 38202657, 2023). "This is a general concern with tumour-associated antigens such as HER2, EGFR and folate receptor." (PMID 37291434, 2023). "The level of EGFR expression is known to be higher in the tumor than in the adjacent normal tissue, but the normal tissue around the tumor may also express EGFR." (PMID 37568610, 2023). "Moreover, we also checked the protein–protein interaction (PPI) network of CAV1 and found it is highly connected with Caveolin-2 and EGFR, which are important factors for tumor progression." (PMID 37642765, 2023). "In contrast, our PPI network results support the hypothesis that SLC31A1 regulates EGFR to promote tumour neovascularisation." (PMID 37853210, 2023). "Furthermore, tumor cell proliferation, measured using the Ki-67 proliferation index and frequently driven by the epidermal growth factor receptor (EGFR), links those markers to tumor growth." (PMID 37894447, 2023). "EGFR mutation also induces upregulation of MDSCs, increases IDO in DCs, and enhances M2-like polarization and migration of TAMs, which abrogates CD8+ T cell and cytotoxic NK cell-mediated tumor killing." (PMID 37345086, 2023). "The authors found that decitabine, a DNA methyltransferase inhibitor, could sensitize gefitinib response, resulting in inhibition of tumor cell growth and apoptosis, as well as decreased EGFR protein expression." (PMID 37895255, 2023). "The extent of EGFR inhibitory effects varied among each of the carcinoma cell lines, which is in line with the varying levels of sensitivity to EGFR-inhibition reported for different tumor types (as reviewed in)." (PMID 37545491, 2023). "Tumor Mutation Burden (TMB) and EGFR/ALK mutations are two promising biomarkers." (PMID 36895477, 2023). "Besides directly promoting tumor cell proliferation, EGFR can also serve as a modulator for tumor immune monitoring, promoting the PD-L1 expression by activating the JAK/STAT3 signaling pathway, inducing T cell apoptosis and immune escape." (PMID 37799727, 2023). "In terms of tumor response, progression-free survival (PFS), and overall survival (OS), anti-EGFR monoclonal antibody with chemotherapy is the most effective treatment for patients with metastatic colorectal cancer (mCRC) whose primary tumor is situated in the left colon or rectum." (PMID 37834263, 2023). "EGFR is an important cancer driver critical for tumor growth and survival." (PMID 37996892, 2023). "Although gefitinib’s anti-tumour effect has yet to be thoroughly characterised, it has been shown to decrease tyrosine kinase activity by competitively binding to the intracellular ATP-binding region of EGFR." (PMID 37375846, 2023). "Furthermore, the in vivo antitumor efficacy of EGFR‐functionalized LNPs (targeting the PLK1 gene) was carried out in the OV8‐mCherry tumor model in mice." (PMID 37166046, 2023). "Furthermore, HCD3514 induced tumor growth inhibition in EGFR19del/T790M/C797S xenograft model as a single oral agent by decreasing the activation of EGFR." (PMID 36605493, 2023). "Several studies have investigated the prognostic significance of the ratio of T790M to major EGFR mutation at baseline in patients with advanced EGFR T790M-positive NSCLC receiving osimertinib and reported that a higher ratio is closely related to tumor shrinkage and favorable survival." (PMID 38012343, 2023). "For example, a virus expressing IL-4 prolonged survival in tumor-bearing mice and one expressing a single-chain variable fragment of the epidermal growth factor receptor (EGFR) antibody conjugated to CCL5 increased the infiltration of innate and adaptive immune cells." (PMID 37509400, 2023).
tumor (continued). "In fact, metastatic CRC (mCRC) was one of the first tumours in which precision medicine was implemented through hotspot KRAS‐NRAS gene sequencing due to its negative predictive value of response to anti‐Epidermal Growth Factor (anti‐EGFR) antibodies." (PMID 37097008, 2023). "Tumor EGFR is also released with EVs in response to anti-EGFR antibody (cetuximab) treatment." (PMID 36671802, 2023). "Targeting lnc-EGFR and its signaling axis may therefore represent a promising strategy to improve the anti-tumor activities of sorafenib and lenvatinib." (PMID 37346034, 2023). "The EGFR-Ras-ERK1/2 pathway also regulates several proinflammatory genes which may affect the tumor microenvironment as discussed later." (PMID 37696458, 2023). "Moreover, in mice co-transfected with both LAMC2 siRNA and EGFR plasmid, tumor size, volume, and weight were substantially reduced compared to the NC group." (PMID 37542131, 2023). "These engineered T cells could target and lyse EGFR+ tumor cells in a TM concentration-dependent manner." (PMID 36761751, 2023). "Nevertheless, the overexpression of tyrosine kinase receptors (TKRs), such as the epidermal growth factor receptor (EGFR), has emerged as associated with TNBC, enhancing tumor cells proliferation, migration, and invasiveness, comprising a potential therapeutic target." (PMID 37568789, 2023). "Likewise, an in silico study performed in the MDA-MB-231 cell line revealed an association between intrinsic PD-L1, the EGFR signaling pathway, and several factors involved in the EMT process and tumor stemness." (PMID 36901916, 2023). "Moreover, the search by NGS for common hotspot mutations (BRAF, EGFR, and KRAS) showed a greater sensitivity if compared to circulating free DNA or circulating tumour DNA." (PMID 37296932, 2023). "A variant example of selective agonism is the creation of CD3 T cell engagers (TCEs) that incorporate antibody binding regions of 4-1BB with CD3, and checkpoint blockade (PD-L1), and a tumor target such as CD19 or EGFR, with the aim of only engaging 4-1BB on a T cell in the TME." (PMID 37662949, 2023). "Oncogenic mutation drivers such as epidermal growth factor receptor (EGFR), anaplastic lymphoma kinase (ALK), and repressor of silencing 1 (ROS-1) can alter the immune tumour microenvironment, which may induce anti-PD1/PD-L1 resistance." (PMID 38132403, 2023). "Knockout of the uPAR gene by CRISPR gene knockout technology can lead to tumor cell apoptosis, increase the sensitivity of tumor cells to chemotherapy drugs, and down-regulate EGFR expression, suggesting that uPAR can be used as a therapeutic target for colon cancer." (PMID 37020597, 2023). "A synergistic effect against tumor cells by combining anti‐EGFR antibody and immunotherapy has been validated in other solid tumors, thus, further supporting the immunologic effect of anti‐EGFR antibodies." (PMID 37537946, 2023). "Furthermore, the combination of lenvatinib and EGFR inhibitors showed an efficient anti‐tumor effect in multiple in vivo HCC models that expressed high levels of EGFR." (PMID 37218919, 2023). "Furthermore, a study on mouse corticotroph tumor cells proved that EGFR inhibitors, already approved for other malignancies, decreased cell proliferation." (PMID 37958474, 2023). "Similarly, DYRK1A inhibition suppressed the EGFR/c-Met signaling in pancreatic cancer, resulting in a decreased tumor growth." (PMID 37900285, 2023). "In addition, better results were obtained by the application of a cutoff point ≥10% tumor cells with EGFR overexpression (p < 0.001)." (PMID 37569265, 2023). "In addition to EGFR activity, increased tumor stemness is one of the hallmarks of cancer and is a key feature of the progression and poor outcome." (PMID 36968199, 2023). "Based on this, we could suggest that 4NSG-SLN may have resulted in a significant decrease in tumor growth and is most likely due to 4NSG's ability to target EGFR, HER2, and VEGFR receptors." (PMID 37179357, 2023).
tumor (continued). "Moreover, the compound is more toxic toward a tumor cell line characterized by an increased level of EGFR expression, i.e., the MDA-MB-231 cell line, which is also characteristic of erlotinib." (PMID 37111769, 2023). "In addition, it is interesting to notice that the PD-1 signaling pathway is activated in EGFR TKI–resistant tumors with increased tumor-stroma interaction." (PMID 36647832, 2023). "This may favor the hepatocarcinogenic process, as observed in different models of hepatic injury ending in HCC, in which pharmacological or genetic inhibition of EGFR prevents tumor development." (PMID 38138981, 2023). "Upon reformatting into Fc effector‐silenced NKCEs targeting NKp46 and EGFR in a strictly monovalent fashion, the resulting bispecific antibodies elicited potent NK cell‐mediated killing of EGFR‐overexpressing tumor cells with potencies (EC50killing) in the picomolar range." (PMID 36775946, 2023). "Activation of the EGFR pathway has been shown to increase the expression of PD-L1 and other immunosuppressive factors, suggesting a role for EGFR signaling pathway in remodeling the tumor microenvironment." (PMID 36894581, 2023). "A universal method to evaluate tumour EGFR status should be adopted." (PMID 38414930, 2023). "However, our results show that both EGFR and ERBB2 play a significant role in PDAC and their loss leads to slowed tumor growth." (PMID 37341059, 2023). "Furthermore, the elimination of EGFR phosphorylation in OS inhibits growth, whereas EGFR overexpression promotes tumor cell invasion." (PMID 36944946, 2023). "Since EGFR is a tumor cell-intrinsic driver alteration, we hypothesized that tumor regions would contain most of the classification signal." (PMID 36927889, 2023). "Our data suggest that among the pathways affecting tumor-intrinsic PD-L1 signaling, BIM is potentially the underlying mechanism that affects the role of PD-L1 expression in predicting response to EGFR TKI and mediates cell apoptosis under treatment with gefitinib in EGFR-mutant NSCLC." (PMID 36894581, 2023). "Overexpression of EGFR thus favors tumor growth and progression." (PMID 38138609, 2023). "Furthermore, HDGF and EGFR have complementary roles in maintaining the survival of tumor cells exposed to gefitinib." (PMID 37301856, 2023). "After activating the EGFR/Ras pathway in tumor cells, JX-594 as an oncolytic poxvirus can enter the tumor cells and proceed to undergo replication, transgene expression, and amplification, eventually inducing cancer cell lysis and triggering antitumor immunity elevation." (PMID 37040283, 2023). "Since this T cell-deserted tumor microenvironment may lead to the refractoriness of ICIs against EGFR-mt LA, we investigated the mechanism by focusing on the regulation of chemokine expression." (PMID 36991099, 2023). "The EGFR variant known as EGFRvIII is highly specific for GBM because it is not expressed in non-tumor tissues and is present in 25–33% of all GBM patients." (PMID 37895074, 2023). "Shutting down phosphorylation pathways by potent TKIs in proliferating cancer cells creates selective conditions for the emergence of different mutants through alternative mechanisms, such as H2O2 release, in the branched EGFR interactome in the tumor microenvironment." (PMID 37754201, 2023). "In summary, the trifunctional antibodies exhibit the following properties: i) dual tumor-targeting by EGFR and PD-L1 binding to increase tumor selectivity, ii) immune checkpoint inhibition by blocking the PD-1/PD-L1 axis, and iii) potent NK cell-mediated cytotoxicity by CD16a targeting." (PMID 37081888, 2023). "Among cancers poorly responding to ICB therapy, the EGFR–mutated lung tumor has been described to achieve a modest advantage in clinical settings, likely due to an insufficient intra-tumor T cell recruitment, speaking in favor of a non-inflamed tumor site." (PMID 37626933, 2023).